CCL4 (C-C motif chemokine ligand 4)
Diseases named in the same sentence as CCL4 in open-access papers (continued):
Sharing a sentence is not in itself a finding about the gene and the disease.
tumor (continued). "Our observations are consistent with previous observations highlighting the role of CCL3 and CCL4 chemokine systems in recruiting antitumor CD103+ DCs to the tumor, especially in the tumor models that respond poorly to CPIs." (PMID 36968220, 2023). "TIGIT can also upregulate the expression of the chemokine CCL4 and the chemokine receptor CCR8, which help with Treg migration and retention in tumor tissue." (PMID 35008385, 2022). "Studies in both humans and mice have shown that these immature monocyte precursors, as well as CD8+ T cells and natural killer (NK) cells are actively recruited into tumors via tumor-derived chemokines (e.g., CCL2/MCP-1, CCL3/MIP-1⍺, and CCL4/MIP-1β)." (PMID 36059473, 2022). "The role of the proinflammatory chemokines MIP1-α (CCL3), MIP1-β (CCL4), and MCP-1 (CCL2) in the tumor remains controversial." (PMID 35359980, 2022). "Consistent with this, the expression of T cell chemokine genes such as CCL3, CCL4, CCL5, CXCL9, CXCL10 and CXCL1123 in MKN74 tumours tends to be higher than that in other tumours, especially after ERY974 administration." (PMID 36071036, 2022). "This was further supported by the high levels of MHC I/II molecules (HLA–B, HLA-C, HLA-DRB1 and HLA-DQA1) expressed in cDC-CD1C-AREG from low tumor infiltration group as well as inflammatory cytokines and chemokines (IL1B, VEGF and CCL4, etc.)." (PMID 36532059, 2022). "The expression levels of other hub genes CTLA4, CXCL10, CCL5, CCl4, ICAM1, CXCL9, CD27, GZMB, FCGR2A, SELL, IDO1 in SKCM were higher than those in non-tumor skin tissues (P < 0.05), and the results were statistically significant." (PMID 35710862, 2022). "During hyperthermia, cells under heat stress enhance immune response by promoting the release of more exosomes rich in tumor antigens, chemokines (including CCL2, CCL3, CCL4, CCL5 and CCL20, etc.)and HSP to APC to identify and destroy tumor cells." (PMID 36032103, 2022). "In contrast, CCL4 positively correlated with routine markers (CEA, CA 19-9), CRP protein, age (similar to CEA), and tumor stage (similar to CEA and CA 19-9)." (PMID 35407400, 2022). "In this study, when we re-stained the tumor specimens with Angpt2 and CD31, we observed that levels of Angpt2 and CD31 expression in excised tumors were significantly decreased in the SAS/CCL4 shRNA cells." (PMID 35884919, 2022). "ATC-like tumor shows high levels of T cell infiltration, chemo-cytokines (CCL2, CCL3, CCL4, CCL5, CXCL9, and CXCL10), and immune checkpoints." (PMID 36293435, 2022). "The B16F10 cells produced large amounts of CCL5/RANTES, whereas the ex vivo s.c. tumour also secreted CCL2/MCP-1 and, at much lower levels, CCL3/MIP-1α and CCL4/MIP-1β." (PMID 36241867, 2022). "The chemokine, CCL4, and the T cells activator, CD83, were also found to be upregulated in the HPV+ tumour-T cell interactions." (PMID 36420261, 2022). "The CD27-positive, CD38-positive, and PAX5-negative tumor-induced plasmablast-like-enriched B cell (TIPB) population regulates T cell-recruiting chemokines (CCL3, CCL4, and CCL5) and increases the number of tumor-infiltrating T cells." (PMID 36361781, 2022). "NK cells can directly kill tumor cells by cytotoxicity and can also exert immune functions indirectly by secretion of cytokines such as IFN-γ, TNF-α, CCL3, and CCL4." (PMID 35707003, 2022). "Macrophage 2 had enriched expression of many chemokines and ligands, including CCL4, CCL4L2, CCL3, and CCL3L1, which were involved in recruiting immune cells to promote tumor development." (PMID 36292645, 2022). "CCL2 had the highest serum level in naïve mice, followed by CCL4 and CCL5, and their concentrations increased from the early to late stage of metastasis, just like in mice with the s.c. tumours." (PMID 36241867, 2022). "A group of cells was shown to highly express CCL4L2, CCL4, and other chemokines and their receptors as well as IL1B, indicating the function of promoting tumor growth." (PMID 36304995, 2022).
tumor (continued). "For instance, CCL4-induced increases in vascular endothelial growth factor (VEGF) expression promote the proliferation, invasion and migration of tumor cells in endometrial cancer and OSCC." (PMID 35884919, 2022). "The transcriptome analysis also revealed that tumor derived factors induced bone marrow cells to transcribe CCL3, CCL4, and other ligands of CCR1 and CCR5." (PMID 35064009, 2022). "In fact, the expression of key neutrophil-secreted chemokines, including CCL3, CCL4, CCL20, and CXCL12, was increased in the tumor supernatants of mice treated with 7HP349." (PMID 35552271, 2022). "In tumor cells with high expression of β-catenin and activation of the WNT pathway, CCL4 secretion is diminished, and the recruitment of DCs into the TME by CCL4 is blocked, thus posing an obstacle to T cell infiltration into the TME75." (PMID 35254013, 2022). "They express checkpoint molecules such as LAG3 but also secrete CCL4 and CXCL13 and thereby attract more Batf3 DCs and B cells into the tumor microenvironment." (PMID 35626062, 2022). "Transcriptome functional and cytokine analysis indicated that tumor derived factors induced CCL3 and CCL4 in HSPCs that, through the autocrine engagement of CCR1 and CCR5, induced HSPCs differentiation in MDSCs." (PMID 35064009, 2022). "Among these, 4 genes (CD8A, CD3E, CCL4 and ITGAL) were reported to have close relationship with tumor immune microenvironment and to be involved in various pathological processes of EC35–37." (PMID 34131259, 2021). "In the present study, inflammation-related chemokines including CCL3 and CCL4 were both increased in cSCC and AK, which helps recruit and CD4+, CD8+ T cell to kill tumor cells." (PMID 33664254, 2021). "While baseline IFNg is higher in the recurrent tumor, the level of TNFa, RANTES (CCL5), IP-10, IL-5, IL-10, MIP1a (CCL3), MIP1b (CCL4), and GM-CSF are all significantly lower in the recurrent tumor." (PMID 34221953, 2021). "CCL4 is a crucial chemokine for CD103+ DC recruitment; however, it is usually lacking in tumor lesions, and the retention of external CCL4 in tumor lesions is still a problem." (PMID 34138315, 2021). "Their interaction with the BMDMs and tumor cells in the collagen-I matrix increased production of GM-CSF, G-CSF, IL-6, CCL2, CCL3, CCL4 and CCL12, and reduced production of IFN-β1, LIF, VEGF, CCL17, CXCL5 and CX3CL1." (PMID 34572807, 2021). "Its ligands CCL3, CCL4, and CCL5 are broadly expressed by a variety of normal cells and tumor cells, and frequently upregulated in tumor tissues of various types of cancer." (PMID 34885241, 2021). "MDSCs produce the CCR5 ligands CCL4 and CCL5, which recruit Tregs to tumor tissues by CCR5 receptors highly expressed on Treg surface." (PMID 34527668, 2021). "Activated NK cells secrete several chemokines, such as CCL4, CCL5 and XCL1, that are responsible for the recruitment into the tumor of CCR5- and XCR1-expressing cDC1s." (PMID 34975880, 2021). "Expression array analysis revealed that both baseline and tumor cell-induced expression of the chemokines CCL3, CCL4, and CCL5 were markedly reduced in MEKK1−/− mammary fibroblasts." (PMID 33868996, 2021). "Other chemokines known to regulate tumor development and progression include the CCR5 receptor ligands CCL3, CCL4, and CCL5." (PMID 33406733, 2021). "CCR5 binds many ligands which are overexpressed in the tumor microenvironment including CXCL13 (BCA-1), CCL3 (MIP1α), CCL3L1, CCL4 (MP-1β), CCL8 (MCP2), CCL11 (eotaxin), CCL13 (MCP-4), and CCL16 (HCC-4)." (PMID 33485378, 2021). "More research is necessary to investigate if similar mechanisms determine tumour-inhibitory vs. pro-tumour effects of CXCL1 and CCL4." (PMID 34359731, 2021). "Additionally, CCL4 was the most connected with other molecules, suggesting that CCL4 could be the key molecule functioning in the immune cell infiltration of the hot tumor subtype." (PMID 33777927, 2021).
tumor (continued). "CCL3, CCL4, and CCL5 binding to the CCR5 receptor promote downstream signaling pathways that facilitate tumor cell proliferation, angiogenesis, metastasis, immune cell recruitment, and repolarization in gastrointestinal cancer." (PMID 33406733, 2021). "A number of studies have shown differential expression of CCR5-related ligands (CCL3, CCL4, CCL5) in peripheral blood and tumor samples of CRC." (PMID 32902795, 2021). "Upregulation of NPTX2 in cold tumor negatively correlated with the expression of CD8A, GZMB, and IFNG, and knockdown of NPTX2 increased the production of CCL4." (PMID 34258887, 2021). "Although blood and tumor-infiltrating NK cells express predominantly perforin and granzyme genes that are related to cytotoxicity, tumor-infiltrating NK cells upregulate XCL1, XCL2, CCL3, CCL4, CCL4L2, and CCL5 that are chemokine genes." (PMID 33424862, 2020). "Mature DCs can also secrete cytokines to foster T cell response and release chemokines such as CXCL9, CXCL10, CCL3, CCL4, and CCL17 to recruit T cells into the tumor bed." (PMID 33505304, 2020). "Tumor-infiltrating NK cells differentiate into two main populations with distinct profiles of chemokine gene expression: XCL1+XCL2+ NK cells and CCL3+CCL4+CCL4L2+CCL5+ NK cells." (PMID 33424862, 2020). "Previous data demonstrate that CCL3 (MIP-1α) and CCL4 (MIP-1b) control the infiltration of the immune cells by recruiting antigen-presenting cells, including dendritic cells (DCs), to the tumor site via IFN-γ." (PMID 33302400, 2020). "In a tumor, an active immune response results in the production of CCL3 and CCL4 by B cells and basophils." (PMID 33076281, 2020). "The interaction of tumor-antigen presenting dendritic cells and CD4+ T helper cells releases chemokine CCL3 and CCL4 that in turn attract CCR5+ cytotoxic CD8+ T cells." (PMID 33414786, 2020). "This study highlights the potential application of neoadjuvant therapy of CBDCA and anti-PD-1 in TNBC patients, and the critical roles of CCL4 and CD103+ DC in CD8+ T cell priming and infiltration in the tumor microenvironment." (PMID 32194569, 2020). "The mRNA expression of different pro-tumor factors such as interleukin-1β (IL-1β), CC-chemokine ligand-2-4 (CCL2, CCL3, CCL4), Interleukin-23 (IL-23) and inducible nitric oxide synthase (iNOS), was analyzed." (PMID 33049964, 2020). "In Ret transgenic mouse models (melanoma model), tumor M-MDSCs also drove the recruitment of CCR5+ Treg cells through producing chemokines such as CCL3, CCL4 and CCL5, further accelerating tumor metastasis." (PMID 33613512, 2020). "Taken together, chemokines such as XCL1, CCL4, and CCL5 secreted by NK cells and activated T cells within the TME recruit cDC1s into the tumor where they efficiently process antigens and then migrate to lymph nodes while they undergo maturation." (PMID 33679726, 2020). "To confirm that CCL3 and CCL4 secretion are sufficient to induce chemoattraction in distant CTLs, we engineered tumour cells that constitutively secrete both chemokines, or CCL3 or CCL4 alone." (PMID 33046212, 2020). "Together, these results indicate that sustained release of CCL3 and CCL4 is sufficient to promote CCR5-dependent homing into tumours in vivo, and that the presence of tumour-reactive CTLs in a tumour promotes the recruitment of distant CCR5+ CTLs." (PMID 33046212, 2020). "Although most chemokines secreted by tumor cells are chemoattractants of pro-tumorigenic immune cells, such as macrophages and Tregs, in certain circumstances, the production of CCL3, CCL4 and CCL5 mediates the recruitment of cDC1." (PMID 32075343, 2020). "It has been shown that CX3CR1+ monocytes are recruited to the tumor cell aggregates in response to tumor-derived CX3CL1, where they can directly engage cancer cells or secrete CCL3, CCL4 and CCL5 to activate natural killer cells to kill CTCs." (PMID 33414786, 2020).
tumor (continued). "At Day 35 after the initial tumor implantation, expression of CD103 and CCL4 was increased in secondary tumors (4T1) treated with CBDCA and anti-PD-1 antibodies." (PMID 32194569, 2020). "Tumor-associated CD8+ T cells expressing exhaustion markers across all four tumor types project onto activated CD8+ T cells in our map, and express genes within the Cytokine module (CCL3, CCL4, XCL1, XCL2, and IFNG), and to a lesser extent Cytotoxic module." (PMID 31624246, 2019). "Tumour hypoxia has been proven to enhance TAM recruitment and infiltration via the hypoxia-induced secretion of chemokines (CCL-4, CCL-8,) and metabolites (lipoxygenase metabolites)." (PMID 31835751, 2019). "The paradigm of tumor intrinsic pathways related to T cell absence into the TME is represented by the WNT/β-catenin pathway, which prevents the expression of C-C Motif Chemokine Ligand 4 (CCL4), a chemokine essential for DC and T cell recruitment." (PMID 30898166, 2019). "We demonstrated that human MSCs secreted high levels of CCR5 ligands (i.e., CCL3, CCL4, and CCL5), and that MSCs promoted CRC tumor growth in vivo via CCR5 signaling." (PMID 30890699, 2019). "The genes that were overexpressed in both senescent thyrocytes and at least one tumor cell line included genes coding for: the chemokines CCL3 and CCL-4, the cytokine IL-1β, the matrix-related protein SPP1, and the enzyme PTGS2." (PMID 31113465, 2019). "Recent studies indicate the critical role of CCL4 and CCL5 within the tumor microenvironment is the recruitment of cells of myeloid lineage that support adaptive anti-tumor T cell responses, such as dendritic cells." (PMID 30873179, 2019). "β-Catenin-mediated immune escape occurs via inhibition of the production of CCL4 derived from tumor cells; this results from induction of the transcriptional repressor ATF3, which blocks CCL4 gene transcription." (PMID 31775797, 2019). "Two additional genes (CD14 and CSNK2A1) were dysregulated in MSS tumours and two genes (CARD11 and VCAM1) were downregulated and six genes were upregulated (LYN, TICAM2, ICAM1, IL1B, CCL4 and PTGS2) in MSI tumours." (PMID 29188362, 2018). "Recently, studies have shown that CD103+ CD11c+ DCs, a subpopulation of dermal- and gut-resident pAPCs, respond to tumor-derived CCL4 and are the chief cells that produce CXCL9 and CXCL10 to recruit tumor-infiltrating T cells." (PMID 29109732, 2017). "Although these studies were primarily focused on CCL4, the production of CCL3 was also significantly increased in their tumor system." (PMID 29109732, 2017). "Our PCR array data showed that both M1-related genes (Ccl2, Ccl3, Ccl4, Ccl5, Il12b, Il1b and Ccl1) and M2-related genes (Il10, Tgfb2 and Il1rn) were significantly upregulated in NM11-shsST2 tumours compared with NM11-shCont tumours." (PMID 27882929, 2016). "Chemokines that work in the favour of recruiting tumour homing cytotoxic T-lymphocytes and macrophages such as GM-CSF, CCL17 and CCL4 were increased specifically in Fe-bLf-Dox treatment." (PMID 27576789, 2016). "Except for PCNA and CCL4 in tumors, Nampt/PBEF/visfatin expression correlated positively with all, both in normal and tumor colonic tissue." (PMID 26075243, 2015). "Of interest, we identified an enrichment of genes involved in the CXCR4 signaling pathway or in the interactions between the CLL tumor cells and their microenvironment (CCL3, CCL4, and CD49d)." (PMID 24883311, 2014). "It is reported that the secretory chemokines CCL3 and CCL4 played an important role in the cross talk between CLL cells and their microenvironment, which promoted the proliferation and metastasis of tumor cells." (PMID 24693884, 2014). "We found that the number of macrophages and levels of IFNγ and CCL4 mRNA were markedly reduced in tumors from CHOP KO relative to wt mice, suggesting a role for CHOP in modulating tumor microenvironment and macrophage recruitment to the tumor." (PMID 24339898, 2013).
tumor (continued). "Hypomethylated genes in the TNF network were cytokines (CCL3, CCL4, CCL7, CCL8, CCL22, IL21, IL17A, EBI3) that can either stimulate or inhibit tumor growth and progression." (PMID 22768131, 2012). "Previously, it was shown that 4T1 cells produce various chemokines, including CCL2, CCL3, CCL4 and CCL5, that we also detected in the tumor microenvironment, with CCL5 levels being significantly higher in tumors in α-TEA-treated mice." (PMID 21232138, 2011). "In contrast, EpCAM, IL8, CXCL10/IP10, CCL3/MIP-1α, CCL4/MIP-1β, CCL15/MIP-1δ, PDGFR-B were predominantly elevated in tumours compared to AN and PN." (PMID 21092330, 2010). "Ligand-receptor interaction analysis further identified predicted interactions between CCR5+ CD8+ T cells and tumor-associated myeloid cells, with elevated expression of CCL3 and CCL4 observed in myeloid populations from non-responsive tumors." (PMID 42278489, 2026). "In addition, the oHSV treatment resulted in higher expressions of Ccl4, Cxcl9, Ccl21 and Cxcl10 in the MC38 tumours." (PMID 39219056, 2025). "CCR5 facilitates T cell migration to inflammatory or infectious sites by binding to chemokines like CCL3, CCL4, and CCL5, particularly crucial in anti-tumor immunity and chronic inflammation, the infiltration of CCR5+ T cells is associated with the efficacy of immunotherapy." (PMID 41438981, 2025). "Similarly, compared to CAF‐S4, CAF‐S5 also upregulates CCL4, CXCL9, CXCL10, CXCL11 and IL1RN suggesting that cytokine and chemokine transcripts are enriched in tumours with high CAF‐S1 and CAF‐S5 and low in the myCAF‐like subset CAF‐S4." (PMID 39743376, 2025). "GABA induced a non-T cell inflammatory tumor microenvironment by inhibiting the activity and infiltration of CD8+ T cells, and it also suppressed the production of chemotactic factors, such as CCL4 and CCL5, which typically recruit T cells and dendritic cells to the tumor site." (PMID 40243466, 2025). "Additional chemokines and growth factors, such as TGF‐α, CCL4, CCL20, IL‐17A, IL‐2RB, and FGF‐23, further underscore the multifaceted interplay between inflammation and tumor biology through pathways ranging from proliferation and angiogenesis to immune cell recruitment." (PMID 41458898, 2025). "The chemokine and receptor profiles of tumor-infiltrating NK1 and NK5 showed increased expression of CCL5, CCL4, XCL1, XCL2, and CXCR3, suggesting that they may be involved in NK tumor homing and activation." (PMID 40315330, 2025). "Since the levels of sCD163 act as surrogates of the TAMs’ tumor burden, and CCL2 along with CCL4 are well-studied chemoattractant cytokines for TAMs’ infiltration, we hypothesize that TAMs play an important role in WM pathogenesis." (PMID 39996747, 2025). "The levels of the myeloid cell-secreted cytokines tumor necrosis factor (TNF), C–C motif chemokine ligand 3 and 4 (CCL3 and CCL4), and monocyte chemoattractant protein- 4 (MCP- 4) increased significantly with treatment, while Galectin- 9, involved in tumor immune evasion, decreased." (PMID 40310569, 2025). "We were surprised to find that CCR5 did not improve in vivo trafficking or survival in tumor bearing mice despite detection of CCL4 in the patient serum and favorable in vitro results." (PMID 41424784, 2025). "Additionally, azvudine regulated the interactions from other tumor immune cells to CD4+ T and CD8+ T cells through ligand‒receptor pairs such as COL1A2‒(ITGA1 + ITGB1), CCL4‒CCR5, CCL6‒CCR2, and CXCL16‒CXCR6." (PMID 39819859, 2025). "Consequently, exogenous CCL4 delivery recruits CD103 + DCs and CD8+ T cells, enhancing the efficacy of immune checkpoint blockade in multiple murine tumor models." (PMID 40429961, 2025). "An agonistic TREM1 monoclonal antibody (PY159) could upregulate the secretion of inflammatory factors such as IFN-γ, CCL3, CCL4, IL-8, and TNF and increased tumor sensitivity to anti-PD-1 therapy in syngeneic mouse tumor models." (PMID 39744496, 2025).